HIF1A (hypoxia inducible factor 1 subunit alpha)
Diseases named in the same sentence as HIF1A in open-access papers (continued):
Sharing a sentence is not in itself a finding about the gene and the disease.
colon carcinoma (367 papers, 2005 to 2025). "Specifically, in human colon cancer tissues, the expression of HIF-1α isoforms—and to a lesser extent, HIF-2α—was associated with the upregulation of VEGF and tumour angiogenesis." (PMID 40917756, 2025). "Here we show that the OC cell lines ES-2, SKOV3 and OVCAR8 under hypoxia show upregulated expression of PLD2, which encodes phospholipase D2, in these cells in a Hif-1α-dependent manner, as recently reported in colon cancer." (PMID 38403587, 2024). "The upregulated expressions of Piezo1 and HIF-1α are closely linked to poor prognosis in patients with colon cancer." (PMID 36615408, 2022). "Carnosine decreased expression of hypoxia inducible factor 1 alpha (HIF-1α) in human colon cancer cells, which is a major cause of resistance to drugs." (PMID 34203479, 2021). "Circulating upregulated miR-210 and miR-21 and downregulated miR-126 expression have shown potential as diagnostic biomarkers for CRC as they are involved in the HIF-1α/VEGF signaling pathways for colon cancer initiation." (PMID 31817259, 2019). "Our results are consistent with another study, showing that OL treatment caused a remarkable decrease in HIF1α protein in human colon cancer cells." (PMID 28057028, 2017). "In HIF-1α deficient colon cancer cells, VEGF-A production is preserved by the pro-angiogenic cytokine IL-8." (PMID 27506944, 2016). "Whereas HIF-1α counteracts c-Myc pathways in cell cycle arrest (proliferation inhibition) of pVHL-deficient, pseudo-hypoxic ccRCC as well as of colon carcinoma, HIF-2α promotes c-Myc activity in pVHL −/− ccRCC." (PMID 26210994, 2015). "In conclusion, we report that HIF-1α inhibition reverses MDR in colon cancer cells, which is associated with downregulation of MDR1/P-gp." (PMID 24901645, 2014). "Activation of hypoxia-inducible factor HIF1A has been associated with poor prognosis in colon cancer." (PMID 20507599, 2010). "In a previous in vitro study with the human colon carcinoma cell line HCT-116 it was demonstrated that HIF-1α regulates the expression of genes encoding proteins involved in the pathophysiology of tumor invasion." (PMID 18983642, 2008). "Specifically, the chemokine IL8 has been shown to underpin the angiogenic response of HIF-1α–deficient/VEGF-depleted DLD-1 colon cancer xenografts, and mediate the resistance of head and neck squamous cell carcinoma and renal cell carcinoma to Bevacizumab and Sunitinib, respectively." (PMID 35302608, 2022). "YTHDC2 may promote the metastasis of colon cancer by promoting the translation of HIF-1α, and YTHDC2 may be a diagnostic marker and target gene for the treatment of colon cancer." (PMID 34124065, 2021). "YTHDC2 results in colon cancer metastasis through augmenting translation of HIF-1α, it may be a potential diagnostic marker and therapy target in colon cancer." (PMID 33015074, 2020). "YTHDC2 can promote cancer metastasis via enhancing the translating efficiency of hypoxia-inducible factor (HIF)-1α in colon tumor cells, and may become a diagnostic marker and target gene for treating colon cancer patients." (PMID 32500031, 2020). "Our data also showed that an elevated ATP5E level in metastatic colon cancer samples was significantly associated with the AMPK-AKT-hypoxia-inducible factor-1α (HIF1α) signaling axis; silencing ATP5E led to the degradation of HIF1α under hypoxia through AMPK-AKT signaling." (PMID 31330880, 2019). "Interestingly, activation of HIF-1α does not result in increased tumorigenesis in a colitis-associated colon cancer model, further suggesting that HIF-1α is a good target for colitis." (PMID 26812949, 2016).
colon carcinoma (continued). "We investigated how the addition of PSK to the medium of cultured colon cancer cell lines affects the expression of the HIF-1α gene, which is closely associated with the expression of angiogenic growth factors, in addition to angiogenic growth factors and angiogenesis." (PMID 23181101, 2012). "Ding suggested that hypoxia induce the expression of HIF-1α and P-gp in colon carcinoma and HIF-1α expression may be associated with P-gp and interactively involved in the occurrence of tumor multidrug resistance." (PMID 21143841, 2010). "Furthermore, ZFP91 is positively associated with HIF-1α in human colon cancer." (PMID 27144516, 2016). "The coimmunoprecipitation and confocal studies showed that PKN2 directly binds to HIF‐1α in colon cancer cells." (PMID 40515512, 2025). "This study reveals that PP extract mitigates the migration, proliferation, and drug resistance of colon cancer cells under hypoxia conditions by inhibiting glycolysis and HIF-1α signaling." (PMID 40647184, 2025). "HSP90 promotes colon cancer invasion and metastasis as well as epithelial-mesenchymal transition through activation of cytokines HIF-1α and NF-κB." (PMID 39911383, 2025). "YC-1 (1–50 μM) similarly inhibits the transcriptional activity of HIF-1α, leading to a reduction in autophagy within colon cancer cells." (PMID 40004215, 2025). "The knockdown of either ONECUT3 or HDAC6 in colon cancer cells led to a marked increase in the acetylation level of HIF-1α." (PMID 40032849, 2025). "To investigate the presence of KynA/P4HA2/VHL/HIF-1α/HILPDA axis in mediating the effects of sleep deprivation on colon cancer, we underwent rescue experiments." (PMID 39920992, 2025). "Inhibiting HIF1A has been shown to sensitize resistant tumors to therapy in various cancer types, including prostate and colon cancers." (PMID 40428339, 2025). "This article “Overexpression of TrpC5 promotes tumor metastasis via the HIF-1α–Twist signaling pathway in colon cancer” DOI: 10.1042/CS20171069 is being retracted from Clinical Science at the request of the authors and the Editorial Board." (PMID 40457657, 2025). "In fact, HIF-1α promoted the growth of SW480 colon cancer cells, while HIF-2α appeared to inhibit growth." (PMID 40917756, 2025). "In conclusion, our results validate the role of the P4HA2/HIF-1α/HILPDA signaling axis in promoting colon cancer progression." (PMID 39920992, 2025). "We demonstrated that PKN2 promotes the ubiquitination and degradation of HIF‐1α in colon cancer cells via direct binding to HIF‐1α." (PMID 40515512, 2025). "Camptothecin, an inhibitor of topoisomerase I, suppresses the stabilization of HIF-1α and autophagy in colon cancer cells at concentrations ranging from 10 to 100 nM." (PMID 40004215, 2025). "In conclusion, our results validate the role of the KynA/P4HA2/VHL/HIF-1α/HILPDA axis in promoting colon cancer progression due to sleep deprivation." (PMID 39920992, 2025). "A study was conducted to investigate HIF-1α-driven colon cancer proliferation, demonstrating that overexpression of HIF-1α enhances tumor growth in colon cancer cells." (PMID 40508113, 2025). "In a mouse lung metastasis model, AAM can reduce the lung metastasis ability of colon cancer cells by downregulating the activation of the HIF-1α/MMP2 signaling pathway." (PMID 40563539, 2025). "To determine if KynA affects HIF-1α ubiquitination, we treated colon cancer cells with a protein synthesis inhibitor cycloheximide (CHX)." (PMID 39920992, 2025). "HIF-1α promotes angiogenesis, metabolic adaptation, and cell survival, leading to colon cancer aggressiveness and tumor growth in the human body through hypoxia-mediated pathways and under normoxic conditions." (PMID 40508113, 2025). "The anticancer effect of EVO in human colon cancer has also been demonstrated, an effect that is partly attributed to its downregulation of Hypoxia-inducible factor 1-alpha (HIF-1α) in cancer cells through inhibition of IGF-1/PI3K/Akt signaling." (PMID 40599807, 2025).
colon carcinoma (continued). "AAM inhibits VM formation in colon cancer cells through the inhibition of the expression of HIF-1α, thereby reducing the pro-angiogenic effect of MMP2." (PMID 40563539, 2025). "The phosphorylation of HIF‐1α was increased in colon cancer cells with high PKN2 expression, while it was decreased in cells with PKN2 knockdown." (PMID 40515512, 2025). "Intravenous administration of high-dose vitamin C (ascorbate) suppressed HIF-1α signaling while targeting hypoxia-induced colon cancer." (PMID 39459028, 2024). "For example, advanced colon cancers expressing both HIF1α and P-gp exhibit higher resistance to chemotherapy." (PMID 39697237, 2024). "Consistently, metronomic cyclophosphamide has been found to offset HIF-1α induction and limit hypoxia in colon cancers." (PMID 38948068, 2024). "This hypoxia-induced autophagy is known to diminish radiosensitivity and resistance to photodynamic therapy via the HIF1A-related pathway in colon cancer cells." (PMID 38240686, 2024). "MCT has been shown to increase Hif-1a, Aldoa, and Pgk1 expression, which implies an upregulation of glycolysis in colon cancer." (PMID 38948068, 2024). "They further conclude that under hypoxia, HIF-1α induces miRNA-210 which in turn enhances autophagy and reduces radiosensitivity by downregulating Bcl-2 expression in colon cancer cells." (PMID 37961749, 2024). "Autophagy levels were described to correlate with HIF-1α expression and have been related to early invasion in colonic carcinoma." (PMID 36939902, 2023). "Overexpression of MYC in human colon cancer and esophageal cancer cells promotes the expression of HIF1A at the post-transcriptional level." (PMID 37998757, 2023). "Further, USP10 knockout increases cellular migration and adhesiveness via activation of HIF-1α signaling especially in colon cancer cells." (PMID 37371055, 2023). "YC-1, as an inhibitor of the HIF-1α transcription factor, prevents the growth of many tumors such as breast cancer, prostate cancer, renal carcinoma, colon cancer and so on." (PMID 37749603, 2023). "It is known that in response to hypoxia, cells can induce HIF-1α-mediated autophagy, leading to increased colon cancer cell survival and reduced cell death after PDT." (PMID 38201494, 2023). "A previous report presented LW1497, a dual inhibitor of MDH1 and MDH2, which showed significant in vivo antitumor effects against colon cancer through the inhibition of mitochondrial respiration and hypoxia-inducible factor-1 alpha (HIF-1α) accumulation." (PMID 37242466, 2023). "Inhibition of HIF-1α improves the sensitivity of colon cancer cells to multiple drugs by downregulating MDR1/P-gp30." (PMID 38007504, 2023). "have shown an increase in HIF-1α protein levels in PMP tissues compared with normal colon samples, as well as an increase in HIF-1α levels in LS174T colon cancer cell line and PMP tissue explants following exposure to hypoxic conditions." (PMID 36776312, 2023). "For instance, in colon cancer, miR-526b-5p downregulates HIF-1α, impedes glycolysis, and represses cancer cell metastasis and proliferation." (PMID 37828032, 2023). "As a hypoxia-inducible gene, ALDOA is a HIF1A target in its transcription and ALDOA gene expression is regulated by HIF1α in several tumors such as lung, liver and colon carcinoma cells with resistance and poor prognosis." (PMID 36077431, 2022). "For example, HIF1-α activates p21 transcription, which blocks the interaction between VHL and HIF1 α, then inhibits the interpretation of HIF1 α, forms a positive feedback regulatory loop, and finally promotes cell growth of colon cancer." (PMID 35652045, 2022). "The knockdown of YTHDC2 in colon cancer cells reduces the expression of metastasis-related proteins such as HIF-1α and inhibits tumor metastasis." (PMID 35155557, 2022). "EMT and IL-6 signaling were also increased in IPA, in addition to colon cancer metastasis signaling, hypoxia-inducible factor 1-alpha (HIF1α) signaling, and the tumor microenvironment pathway." (PMID 35267605, 2022).
colon carcinoma (continued). "Under hypoxic conditions, PrPC leads to cancer progression in colon cancer by targeting the HSP 70 member 1-like (HSPA1L)/HIF-1α/glycoprotein 78 (GP78) axis." (PMID 35885540, 2022). "Another study has reported that treating colon cancer cell lines with A3AR antagonists blocks both HIF-1α and VEGF expression in hypoxic conditions." (PMID 34750517, 2022). "IPA also showed increased EMT and IL-6 signaling, similar to the findings of GSEA, along with increase in HIF1α and colon cancer metastasis signaling, suggesting that MAC had a worse prognosis." (PMID 35267605, 2022). "In terms of the mechanism, ZFP91 functions as a driver gene to activate NF-κB/p65, which results in the upregulation of HIF-1α expression, ultimately leading to the excessive proliferation of colon cancer cells." (PMID 36358661, 2022). "In contrast, circRNA_100859 is overexpressed in colon cancer tissues and suppresses apoptosis by downregulating HIF1A." (PMID 36230902, 2022). "HIF-1α induced autophagy has been shown to be reduced with down-regulation of VMP1 in human colon cancer cell lines." (PMID 35562897, 2022). "LncRNA HITT (HIF1A inhibitor at translation level) directly interacts with ataxia-telangiectasia mutated (ATM) and suppresses homologous recombination repair in human colon cancer tissues." (PMID 36230902, 2022). "Resveratrol, a natural phenol with antioxidant properties, reduced the expression of HIF-1α by scavenging ROS, leading to suppressed glucose uptake and glycolytic metabolism in colon cancer cells." (PMID 33542787, 2021). "Under hypoxia, quercetin treatment reduced the activity of HIF-1α and enhanced apoptosis in colon cancer cells." (PMID 33542787, 2021). "It is reported that L-carnosine treatment decreased the HIF-1α protein levels and suppressed the proliferation of colon cancer cells." (PMID 33542787, 2021). "Based on several studies, inhibition of Nrf2 leads to decreasing HIF-1α protein levels in colon cancer through stimulating proteasomal degradation and the suppression of glucose uptake in colon cancer cells." (PMID 34946740, 2021). "Experiments carried out in colon cancer cell lines (DLD1 and HCT-116) mutated for KRAS have shown that a knock-out or -down of KRASMUT cells impaired the hypoxic induction of HIF-1α." (PMID 33691728, 2021). "This kind of HIF-1α activity was detected in colon cancer, malignant pleural mesothelioma, non-small cell lung cancer (NSCLC), TNBC and chronic lymphatic leukemia cells." (PMID 33423689, 2021). "In colon cancer cells, blocking HIF-1α has been shown to reverse multi-drug resistance via downregulation of P-glycoprotein." (PMID 34503254, 2021). "HIF-1a promoter is normally repressed by methylation, but abnormal demethylation was reported in colon cancer." (PMID 33761933, 2021). "Oncogenic KRAS is involved in mitochondrial metabolism through HIF-1α, as demonstrated in human colon cancer cells." (PMID 33691728, 2021). "YTHDC2 promotes the metastasis of colon cancer cells by facilitating the translation of hypoxia inducible factor 1 subunit alpha (HIF-1α) and twist family BHLH transcription factor 1 (Twist1) mRNA during hypoxia." (PMID 33928028, 2021). "YTHDC2 has been reported to contribute to colon cancer metastasis by promoting the translation of HIF-1α and its related pathways." (PMID 34326699, 2021). "In colon tumour cells, HIF-1α can regulate IL-6 expression via miR-338-5p.However, under hypoxic stress, the HIF-1 complex can promote the transcription and expression of neuronal pentraxin II (NPTX2)." (PMID 35004308, 2021). "The proteins that interact with NQO1 are diverse, and a recent study revealed the NQO1-induced stabilization of hypoxia-inducible factor-1α (HIF-1α) in colon tumors from murine xenografts, via the mechanism of impaired proteasomal HIF-1α degradation." (PMID 34947831, 2021). "Under hypoxia in colon cancer cells, the HIF-1α-dependent expression of miR-210 ensured the radioprotective mechanism involving autophagy and Bcl-2." (PMID 33806538, 2021).
colon carcinoma (continued). "To test how impaired responsiveness of tumor cells to hypoxia affects tumorigenesis, we tested the growth of mouse colon carcinoma cells (MC-38) with stable down-regulation of HIF-1α (HIF-1α-KD) in an orthotopic model." (PMID 33142239, 2020). "Upregulation of miR-210 and miR-21 and downregulation of miR-126 expression are potential CRC biomarkers because of their participation in HIF-1α/VEGF signaling during the initiation of colon cancer." (PMID 32974184, 2020). "In H2052 cells, palbociclib inhibited also HIF-1α expression and prevented its accumulation under hypoxia, confirming previous findings showing that palbociclib destabilizes HIF-1α in colon cancer cells." (PMID 32708306, 2020). "In contrast, tumor-promoting roles have been described for HIF-1α while HIF-2α inhibited tumorigenesis in colon cancer." (PMID 32733884, 2020). "Our results indicate that PIC–BSA NPs were more effective in downregulating the expression of nuclear p65 and HIF-1α in colon cancer cells as compared to free PIC." (PMID 31906321, 2020). "For example, Cys-18 was found to be S-sulfenylated when colon cancer cells were exposed to hydrogen peroxide, resulting in the formation of a covalent complex with HIF1α via disulfide bonding." (PMID 33122195, 2020). "HIF-1α was up-regulated in high or low-differentiation colon cancer tissues compared to adjacent normal tissues, which was verified by qRT-PCR and western blots." (PMID 32152662, 2020). "When exploring tumor databases, we demonstrated that colon tumors exhibit distinct levels of macrophage infiltration, where the most infiltrated tumors are also the most hypoxic ones, presenting higher levels of HIF1A, CA9, and LOX expression." (PMID 32231135, 2020). "For example, HIF-1α promoted the growth of SW-480 colon cancer cells while HIF-2α suppressed the tumor growth." (PMID 32322559, 2020). "Consistent with previous studies, in the present study, HIF-1α expression was up-regulated in colon cancer tissues." (PMID 32152662, 2020). "In our Lab, a previous work on colon cancers showed a high inhibition of HIF-1α with irinotecan in microenvironments varying oxygen concentrations from 5 to 1%." (PMID 33092063, 2020). "While, the epithelial disruption of HIF-2α significantly decreased neutrophil infiltration in colon cancer, HIF-1α stabilization in proximal colon augments inflammation and cancer progression." (PMID 33142239, 2020). "Analysis of colon cancer cell lines revealed that KRAS G12V induces HIF1A hypoxia sensor transcription and, in turn, overexpressed HIF1A or hypoxia activates KRAS signaling." (PMID 32545208, 2020). "We also demonstrated that VMP1-mediated autophagy is induced by HIF-1A (hypoxia inducible factor 1 subunit alpha) in colon-cancer tumor cell lines, conferring resistance to photodynamic treatment." (PMID 32655498, 2020). "This drug, classically considered to be a DNA-damaging agent, was downregulated HIF-1α target genes along with a stark reduction of HIF-1α protein in the xenografted colon cancers." (PMID 33092063, 2020). "It has been reported that IGF1 can stimulate VEGFA mRNA expression by stabilizing HIF1A protein in human colon cancer cell line HCT116." (PMID 32041892, 2020). "Activated HSCs induced HIF-1α mRNA and protein expression in colon cancer cells (p < 0.01) and promoted cell migration (p < 0.01)." (PMID 32895059, 2020). "HIF-1α itself plays an important role in the modulation of CD4+ T cell functions under hypoxic conditions in colon cancer mice cell cultures and can decrease T cell immunity." (PMID 32033172, 2020). "Pin1 directly interacts with HIF-1α at both exogenous and endogenous levels to stabilize the HIF-1α protein in human colon cancer cells and upregulating expression of VEGF, a major contributor to angiogenesis." (PMID 32296699, 2020).